BPHL (biphenyl hydrolase like)
Description:
Specific alpha-amino acid ester serine hydrolase that prefers small, hydrophobic, and aromatic side chains and does not have a stringent requirement for the leaving group other than preferring a primary alcohol. Has homocysteine-thiolactonase activity (in vitro) and may play a significant role in the detoxification of homocysteine thiolactone in vivo. Catalyzes the hydrolytic activation of amino acid ester prodrugs of nucleoside analogs such as valacyclovir and valganciclovir, converting them into their active forms (acyclovir and ganciclovir).
Synonyms: Bph-rp; MCNAA; VACVase
Tractability: Small molecule: a structure with a bound ligand is known; a high-quality ligand is known; it has a high-quality binding pocket. Antibody: UniProt predicts a signal peptide or a membrane-spanning region. PROTAC: ubiquitination databases record sites on it; its protein half-life has been measured.
Target class: Enzyme; Hydrolase
Gene: Protein-coding gene on chromosome 6 (3,118,374 to 3,153,599, forward strand). Ensembl gene ENSG00000137274.
Subcellular location: Mitochondrion
Subcellular location (Human Protein Atlas): Mitochondria
Pathways (Reactome):
Metabolism: Phase I - Functionalization of compounds
Gene Ontology:
Molecular function: alpha-amino-acid esterase activity; serine hydrolase activity
Biological process: homocysteine metabolic process; xenobiotic metabolic process; amino acid metabolic process; response to toxic substance
Cellular component: mitochondrion; mitochondrial outer membrane
Genetic constraint (gnomAD): Loss-of-function variants: 27 observed, 29.5 expected, observed/expected ratio (o/e) 0.92, 90% interval 0.67 to 1.26. The upper end of that interval is the gene's LOEUF score, 1.26, which puts it in group 5 of 6, group 1 being the genes least tolerant of losing a copy. Missense variants: 354 observed, 360.72 expected, observed/expected ratio (o/e) 0.98, 90% interval 0.9 to 1.07. Synonymous variants: 150 observed, 143.25 expected, observed/expected ratio (o/e) 1.05, 90% interval 0.92 to 1.2.
Homologues: Orthologues: chimpanzee BPHL (99% identical), guinea pig BPHL (88% identical), rabbit BPHL (87% identical), dog BPHL (87% identical), mouse Bphl (81% identical), macaque BPHL (80% identical), rat Bphl (80% identical), tropical clawed frog bphl (57% identical), pig BPHL (56% identical), zebrafish BPHL (53% identical), Drosophila melanogaster CG5377 (40% identical), Caenorhabditis elegans C31H5.1 (16% identical), and 6 more. Paralogues in human: EPHX2 (21% identical), EPHX4 (21% identical), ABHD14B (19% identical), EPHX3 (19% identical), ABHD8 (18% identical), ABHD14A (17% identical), ABHD6 (16% identical), ABHD5 (16% identical), MEST (16% identical), ABHD11 (15% identical), SERHL2 (15% identical), ABHD4 (12% identical).
Diseases named in the same sentence as BPHL in open-access papers:
BPHL is named in the same sentence as 5 diseases in open-access papers, as found by Europe PMC text mining. Sharing a sentence is not in itself a finding about the gene and the disease. The quoted sentences say what the papers report.
breast carcinoma (2 papers, 2011 to 2025). "Byphenyl hydrolase-like (BPHL) was initially identified in human breast cancer and is characterized as a serine hydrolase similar to those that degrade biphenyl compounds in prokaryotes." (PMID 40558997, 2025). "This included VACVase, which is a biphenyl hydrolase-like protein originally identified from human breast carcinoma and is usually produced in large amounts in the liver." (PMID 21876742, 2011).
lung adenocarcinoma (1 paper, 2024). A carcinoma that arises from the lung and is characterized by the presence of malignant glandular epithelial cells. "In lung adenocarcinoma cell lines, knockdown of BPHL gene expression through RNA interference resulted in a decrease in tumor growth, colony formation, and metastasis, while promoting an increase in apoptosis." (PMID 39038036, 2024).
infection (1 paper, 2019). The state of being infected such as from the introduction of a foreign agent such as serum, vaccine, antigenic substance or organism. "Compared to C. albicans SC5314 infection, EGFR triggers two proteins BPHL and AVEN." (PMID 30769958, 2019).
BPHL also shares sentences with these, for which no sentence is quoted: tumor (3 papers); lung carcinoma (2).